RNU1-49P (RNA, U1 small nuclear 49, pseudogene)
Gene: Small nuclear RNA gene on chromosome 4 (41,771,945 to 41,772,103, reverse strand). Ensembl gene ENSG00000200338.
Homologues: Orthologues: chimpanzee U1 (100% identical), macaque U1 (92% identical). Paralogues in human: RNU1-89P (75% identical), RNVU1-6 (75% identical), RNU1-1 (74% identical), RNU1-2 (74% identical), RNU1-27P (74% identical), RNU1-28P (74% identical), RNU1-3 (74% identical), RNU1-4 (74% identical), RNVU1-18 (74% identical), RNVU1-29 (74% identical), U1 (74% identical), RNU1-11P (74% identical), and 134 more.